HAVCR2 (hepatitis A virus cellular receptor 2)
Diseases named in the same sentence as HAVCR2 in open-access papers (continued):
Sharing a sentence is not in itself a finding about the gene and the disease.
lung adenocarcinoma (61 papers, 2016 to 2025). A carcinoma that arises from the lung and is characterized by the presence of malignant glandular epithelial cells. "For example, HAVCR2/TIM-3 is expressed by T cells to enforce a crucial immune checkpoint function associated with acquired resistance to anti–PD-1 therapy in lung adenocarcinoma." (PMID 39808498, 2025). "[Objective] Using multi-omics research methods to explore cytolytic activity-related genes through the immunoregulatory factors HAVCR2 (TIM3) affecting the survival and prognosis of lung adenocarcinoma." (PMID 36140350, 2022). "In comparison, low HAVCR2 expression was observed in lung adenocarcinoma (LUAD), pancreatic adenocarcinoma (PAAD), and lung squamous cell carcinoma (LUSC)." (PMID 36081997, 2022). "Immune‐checkpoint molecules PD‐1, LAG3, CTLA4, TIGIT, and HAVCR2 (TIM‐3) have been identified and studied in various cancers including liver hepatocellular carcinoma, lung adenocarcinoma, stomach adenocarcinoma, ovarian cancer, and peritoneal carcinoma." (PMID 35184420, 2022). "[Conclusions] HAVCR2 (TIM3) immunoregulatory factors affect the expression of key genes that affect cytolytic activity in lung adenocarcinoma cells, and to some extent indirectly affect the survival and prognosis of patients with lung adenocarcinoma." (PMID 36140350, 2022). "Finally, we found that COL11A1 is positively correlated with HAVCR2(TIM3), CD274 (PD-L1), CTLA4, and LAG3 in lung adenocarcinoma." (PMID 38649961, 2024). "In addition, we found that the correlation coefficient between CMTM6 and the other three immune checkpoints (PD-L2, HAVCR2 and CD200R1) in lung adenocarcinoma was higher than that between CMTM6 and PD-L1." (PMID 36643629, 2023). "However, in lung adenocarcinoma, there is no report on the relationship between CMTM6 and PD-L2, HAVCR2 and CD200R1." (PMID 36643629, 2023).
ovarian carcinoma (57 papers, 2013 to 2026). A malignant neoplasm originating from the surface ovarian epithelium. "The TISIDB database assessed that CX3CR1 gene expression was significantly associated with immunoinhibitors in epithelial ovarian cancer, including HAVCR2 (R = 0.51, P < 2.2e−16) and CSF1R (R = 0.66, P < 2.2e−16)." (PMID 38241595, 2024). "We then evaluated correlation of T cell exhaustion biomarkers PD1 (PDCD1), CTLA4, LAG3 and HAVCR2 with the expression of CD47 in ovarian cancer." (PMID 34966389, 2021). "We found that AXL and MERTK were expressed at higher levels in liver tissue, lung tissue, endometrial tissue; CD47 was up‐regulated in breast tissue, lung tissue, ovarian cancer, pancreatic cancer and endometrial cancer; and HAVCR2 showed higher expression in renal clear cell carcinoma." (PMID 40576208, 2025). "HAVCR2 is significantly overexpressed in CD4+and CD8+T cells and suppress the antitumor immune responses in primary ovarian cancer, the blockade of HAVCR2 leads to sustained antitumor reactions." (PMID 34484333, 2021).
Sepsis (53 papers, 2012 to 2026). Sepsis is defined as life-threatening organ dysfunction caused by a dysregulated host response to infection. "Immune checkpoint-related genes CD274 (PD-L1), HAVCR2 (TIM3), and SIGLEC15 were overexpressed in sepsis." (PMID 35844488, 2022). "Our analysis showed that multiple immune checkpoints (CD274 [coding PD-L1], HAVCR2 [coding TIM3], and SIGLEC15 [coding SIGLEC-15]) were also highly expressed in sepsis." (PMID 35844488, 2022).
Autoimmunity (46 papers, 2009 to 2026). The occurrence of an immune reaction against the organism's own cells or tissues. "The Tim-3-encoding gene HAVCR2 is located at 5q33.2 in the human genome, a region that has been linked to asthma, allergy, and autoimmunity." (PMID 30309387, 2018). "When it comes to autoimmunity, HAVCR2 exhibits potential protection, but it is rarely expressed, while when it comes to cancer and chronic viral infections, it is often over expressed." (PMID 38240708, 2024). "The TIM-3 gene, HAVCR2, is located in 5q33.2 of the human genome, which is related to asthma, allergies, and autoimmunity." (PMID 35669786, 2022). "The HAVCR2/TIM-3 molecule has been described as a checkpoint inhibitor and key regulator of the immune response acting by inhibiting T cell responses in both autoimmunity and cancer initiation and progression, as well as suppressing macrophage activation following PD-1 inhibition." (PMID 36980527, 2023). "AMS cells showed decreased expression of Hepatitis A virus Cellular Receptor 2/TIM-3, which regulates Treg17 cells and may play a role in preventing autoimmunity." (PMID 36778367, 2023).
non-small cell lung carcinoma (46 papers, 2013 to 2026). A group of at least three distinct histological types of lung cancer, including non-small cell squamous cell carcinoma, adenocarcinoma, and large cell carcinoma. "TIM-3 (CD366 or HAVCR2) is expressed on highly dysfunctional T cells, and TIM-3-associated drug resistance has been observed in HNSCC and non-small-cell lung cancer (NSCLC)." (PMID 35392063, 2022).
colon carcinoma (45 papers, 2015 to 2025). "We found that common checkpoints such as CD274, CEACAM1, HAVCR2, and CTLA4 in the treatment of colon cancer were significantly correlated with risk score." (PMID 34840571, 2021). "We selected immune checkpoints common in colon cancer therapy for analysis, finding that CD274, PDCD1, and HAVCR2 were positively correlated with the risk score." (PMID 34840571, 2021). "As opposed to the low-risk colon cancer patients, the high-risk cases showed higher expressions of CTLA-4 (p < 0.001), PD-1 (p < 0.01), PD-L1 (p < 0.001), IDO1 (p < 0.05), IDO2 (p < 0.05), HAVCR2 (p < 0.001), and LAG3 (p < 0.05)." (PMID 36280825, 2022).
lymphoma (45 papers, 2013 to 2025). A malignant (clonal) proliferation of B- lymphocytes or T- lymphocytes which involves the lymph nodes, bone marrow and/or extranodal sites. "To elucidate if HAVCR2 mutations are only limited in SPTCL patients or if there is heterogenicity in various lymphoma types, we explored the change and significance of HAVCR2 mutations in T-cell or B-cell lymphoma." (PMID 36212426, 2022). "WES revealed significantly mutated genes, including several known (NCF1, MMP9, and VDR) and possibly other candidate (CNN2, MUC4, MTSS2, KMT2C, HAVCR2, and TCF19) genes, most of which were associated with the physiological activation of lymphoma cells." (PMID 41296384, 2025). "Second, germline mutations may predispose individuals to both lymphoma and HLH, for instance, germline HAVCR2 mutations promote the development of HLH and subcutaneous panniculitis-like T cell lymphoma." (PMID 36032133, 2022). "However, the occurrence of the HAVCR2 mutations and the specificity on lymphoma classification or clinical features have not yet been fully elucidated." (PMID 36212426, 2022).
osteosarcoma (45 papers, 2013 to 2025). A usually aggressive malignant bone-forming mesenchymal neoplasm, predominantly affecting adolescents and young adults. "CircPVT1 orchestrates osteosarcoma migration and invasion by regulating the miR‐490‐5p/HAVCR2 axis, underscoring its potential as a promising therapeutic target for osteosarcoma." (PMID 38568056, 2024). "Overexpression of miR‐490‐5p led to a significant attenuation of migration and invasion of osteosarcoma cells, whereas HAVCR2 overexpression had the opposite effect, promoting these abilities." (PMID 38568056, 2024). "Previous studies have also found that CD44, CD40, PDCD1LG2, LAG3, and HAVCR2 can be immunotherapeutic targets for osteosarcoma." (PMID 38071320, 2023). "Downregulation of HAVCR2 acted as a risk factor in CESC, KIRC, osteosarcoma, and SKCM, while it was protective in GBM, GBMLGG, LGG, PRAD, and UVM." (PMID 36081997, 2022). "Additionally, circPVT1 upregulated HAVCR2 expression via sequestering miR‐490‐5p, thereby orchestrating the migration and invasion in osteosarcoma cells." (PMID 38568056, 2024). "In this study, we noted a higher expression level of the ICGs (CTLA4, CD274, PDCD1C, HAVCR2, and LAG3) in the osteosarcoma patients categorized into the low‐risk group, which suggested that these patients could gain more benefits from the immune checkpoint blockade therapy." (PMID 36129020, 2023). "In the same study, HAVCR2 was found to have a prognostic role in CESC, KIRC, SKCM, and osteosarcoma, and an adverse role in the prognosis of GBM, GBMLGG, LGG, PRAD, and UVM." (PMID 39064019, 2024). "These outcomes indicated that HAVCR2 expression was a protective factor in CESC, KIRC, SKCM, and osteosarcoma." (PMID 36081997, 2022). "Relatively low expression levels of CTLA4, HAVCR2, LAG3, and PDCD1LG2 can be observed in the group of patients with metastasis (p < 0.05), which may indicate and predict a poor prognosis in patients with osteosarcoma." (PMID 38256356, 2024).
glioblastoma (42 papers, 2019 to 2026). The most malignant astrocytic tumor (WHO grade IV). "Gene expression analysis of in-house glioblastoma samples confirmed that HAVCR2 expression was higher than other well-known immune checkpoint inhibitors such as CTLA4, PD-1, PD-L1, PD-L2, and IDO1." (PMID 40072074, 2025). "The analyses identified only 7 out of 121 immune checkpoint markers (including HAVCR2/TIM-3) with elevated expression in glioblastoma compared to controls." (PMID 40072074, 2025). "One immunoregulatory molecule that has not been thoroughly targeted in glioblastoma-based clinical trials is T cell immunoglobulin and mucin domain-containing protein 3 (TIM-3, encoded by the HAVCR2 gene)." (PMID 39513882, 2024). "Similarly, our subsequent analysis of single-cell RNA-Seq data from Neftel and colleagues revealed that HAVCR2 (TIM-3) expression was detected in most T cells (81%) in the glioblastoma micro-environment and was correlated with low expression of BAG6 (BAT3)." (PMID 39513882, 2024). "Qi and colleagues demonstrated that an eight-gene risk signature based on fatty acid catabolic metabolism in glioblastoma had high prognostic value and that this signature significantly correlated with gene expression of the immune checkpoint markers B7-H3 (CD276) and HAVCR2 (TIM-3)." (PMID 40072074, 2025). "Reinforcing these results, a strong and positive correlation was observed between HAVCR2 and ENTPD1 expression levels in glioblastoma patients." (PMID 39513882, 2024). "Interestingly, HAVCR2 gene expression is correlated with the progression-free, but not overall, survival of glioblastoma patients." (PMID 39513882, 2024). "Moreover, elevated HAVCR2 (but not ENTPD1) expression levels were significantly associated with reduced progression-free survival (PFS), but not overall survival for glioblastoma patients." (PMID 39513882, 2024).
liver cancer (41 papers, 2018 to 2025). An epithelial or non-epithelial malignant neoplasm that arises from the liver. "Analysis of 21 trogocytosis‐related proteins identified three with causal associations to liver cancer: HAVCR2, CD274, and C3." (PMID 40895144, 2025). "HAVCR2 or TIM-3, plays a key role in immune regulation and is an independent indicator of poor prognosis in liver cancer." (PMID 39640777, 2024). "There are ongoing phase-II clinical trials (NCT03680508) using TSR-042 PDCD1 (PD-1) and TSR-022 anti-HAVCR2 (TIM3) antibodies for primary liver cancer." (PMID 38248311, 2023). "More and more studies have been conducted on HAVCR2 as a target for liver cancer immunotherapy." (PMID 38890507, 2024). "In order to identify novel immune biomarkers from the TCGA-LIHC and examine associated expression with established immune biomarkers for T cell activation with an immune checkpoint inhibitor in liver cancer, this study examined PDCD1, CTLA4, HAVCR2, and LAG3." (PMID 38248311, 2023). "The results showed that these genes were highly expressed in liver cancer including CD80, CD44, HAVCR2, NRP1, and LAIR1." (PMID 35067176, 2022). "In contrast, deletion of Tox in CD8+ TIL prevents exhaustion via decreased chromatin accessibility and expression of Pdcd1, Havcr2 (Tim-3), Cd244 (2B4), and Tigit (TIGIT) in the SV40-Tag-driven autochthonous liver cancer model." (PMID 34354714, 2021).
cervical carcinoma (38 papers, 2013 to 2025). A carcinoma arising from either the exocervical squamous epithelium or the endocervical glandular epithelium. "Overexpression SUV39H1 also associated with increased methylation level of HAVCR2 and LGALS9 which in turn caused Tim-3 and galectin-9 expression decreased in cervical cancer." (PMID 32699524, 2020). "Similarly in cervical cancer, increased HAVCR2 expression is linked to advanced tumour grades, poor overall survival and metastatic potential." (PMID 38568056, 2024). "Conversely, hypomethylation of HAVCR2 and LGALS9 promoters, encoding the immunosuppressive molecules Tim-3 and galectin-9, increases their expression in cervical cancer cells, fostering an immunosuppressive TIME and correlating with poorer overall survival." (PMID 41029427, 2025). "Tim-3 and galectin-9 are overexpressed in cervical cancer cases, which is mediated through the hypomethylation of HAVCR2 and LGALS9 because of the lesser expression and recruitment of DNMT3A to their promoter regions." (PMID 36766706, 2023). "Knocked-down DNMT3A in cervical cancer cells caused a decreasing of HAVCR2 and LGALS9 methylation level, accompanied by the expression of Tim-3 and galectin-9 elevated." (PMID 32699524, 2020). "Hence HAVCR2 has a positive correlation with LGALS9 in cervical cancer." (PMID 32699524, 2020). "HAVCR2 and LGALS9 promoter regions in cervical cancer tissues displayed hypermethylation status in normal cervical tissues, possibly leading to the inhibition of transcriptional activity of genes in normal cervical tissues." (PMID 32699524, 2020). "The methylation status of HAVCR2 and LGALS9 were detected by MS-PCR in cervical cancer tissues and cell lines." (PMID 32699524, 2020). "The results indicated that the expression levels of HAVCR2 and LGALS9 were all higher in cervical cancer than in normal cervical samples." (PMID 32699524, 2020). "DNMT3A involved in the induction of genes expression by directly binding to the HAVCR2 and LGALS9 promoter regions, suggested that DNMT3A participate in the epigenetic regulation of HAVCR2 and LGALS9 in cervical cancer." (PMID 32699524, 2020). "After have been determining the baseline levels of DNA methylation on HAVCR2 and LGALS9 promoter regions among cervical cancer cell line, evaluation whether SUV39H1 mediated DNA methylation through DNMT3A is required for HAVCR2 and LGALS9 transcription." (PMID 32699524, 2020).
malaria (33 papers, 2016 to 2025). Malaria is a serious and sometimes fatal disease caused by a parasite that commonly infects a certain type of mosquito which feeds on humans. "Evidence of malaria induced immunosuppression within our data was also observed in NK and γδ T cell subsets, where multiple co-inhibitory receptors were upregulated during infection (including TNFRSF4, TNFRSF9, TNFRSH18, HAVCR2, LAG3, and PDCD1)." (PMID 37968278, 2023).
pancreatic cancer (29 papers, 2013 to 2025). "Approximately 40% to 70% of CD8A+ T lymphocytes co-expressed PDCD1 and/or HAVCR2 in both IF and TC, independently of the neoadjuvant chemotherapy, suggesting that T cytotoxic lymphocytes are exhausted in the pancreatic cancer microenvironment." (PMID 32645996, 2020). "Further RT-qPCR analysis of mouse tumor tissues demonstrated that knockdown of the ETV4 gene resulted in reduced FGL1 expression and no significant changes in HAVCR2, consistent with the results observed in BxPC3 pancreatic cancer cells." (PMID 40469297, 2025). "Although we found HAVCR2 and CFTR cited together in a 2019 paper related to pancreatic cancer, their ratio does not seem biologically meaningful." (PMID 33572894, 2021).
head and neck squamous cell carcinoma (28 papers, 2017 to 2026). A squamous cell carcinoma that arises from any of the following anatomic sites: lip and oral cavity, nasal cavity, paranasal sinuses, pharynx, larynx, and salivary glands. "In the analysis of immune checkpoint (IC) genes, PLAG1 exhibits a positive correlation with key IC genes such as HAVCR2 and CD274 in cancer types like LGG and PRAD, while showing a negative correlation in head and neck squamous cell carcinoma (HNSC) and STAD." (PMID 40276502, 2025).
HIV-1 infection (23 papers, 2012 to 2025). The type species of lentivirus and the etiologic agent of acquired immunodeficiency syndrome (AIDS). "The minor G allele at rs4704846 was found to increase HAVCR2 expression after in vitro HIV-1 infection." (PMID 25180498, 2014). "Furthermore, some reports have shown that T-cell immunoglobulin and mucin domain 3 (TIM-3) (encoded by HAVCR2 gene), a negative regulator of the activation of Th1 and Th17 cells can reduce HIV-1 infection in vitro." (PMID 28243241, 2017). "Thus, a positively selected polymorphism in the 3′ UTR, which modulates HAVCR2 expression, is associated with the susceptibility to HIV-1 infection." (PMID 25180498, 2014).
sarcoma (23 papers, 2013 to 2025). A usually aggressive malignant neoplasm of the soft tissue or bone. "T‐cells in the sarcoma microenvironment exhibited elevated levels of cytotoxicity (GZMB, GNLY and KLRD1), exhaustion (HAVCR2, CD38, CD160, CXCL13 and CX3CR1), and inflammation (IL33, PPARG, IL6R and SOCS3), suggesting an activated but exhausted phenotype." (PMID 39658531, 2024). "Finally, the results of immune checkpoints’ expression showed significant differences in CD274, HAVCR2, PDCD1, and TIGIT between the two subtypes, and m7GRGs might be a predictive marker for the treatment of sarcomas by targeting immune checkpoints." (PMID 36816047, 2023).
head and neck cancer (22 papers, 2015 to 2025). A primary or metastatic malignant neoplasm affecting the head and neck. "In a meta‐analysis of nine datasets of head and neck cancer gene expression profiling, HAVCR2 (gene encoding TIM3) DNA copy number and mRNA expression were both significantly increased in HNSCC as compared with the controls (P < 0.001)." (PMID 28102051, 2017). "HAVCR2/TIM-3 expression is upregulated in tumour-infiltrating lymphocytes in head and neck cancer and other neoplasms of different origin." (PMID 36980527, 2023). "HAVCR2 is overexpressed in the TILs in gastric, lung, and head and neck cancers." (PMID 35198632, 2022).
bladder cancer (19 papers, 2017 to 2025). "Though the signature was only significantly associated with ICI-related biomarkers like TNFRSF9, instead of CTLA4, LAG3, HAVCR2 and PDCD1, thus proving that the efficacy of immunotherapy still presents an underprivileged position within the treatment of bladder cancer." (PMID 34322391, 2021).
clear cell renal cell carcinoma (19 papers, 2016 to 2026). "Several studies have shown that HAVCR2 is significantly upregulated in clear cell renal carcinoma, bladder urothelial carcinoma, and STAD and is associated with poor prognosis in cancers." (PMID 37370118, 2023). "We discovered that ACSL3 is substantially associated with the immune checkpoint inhibitors PD-1, PD-L1, CTLA4, LAG3, and HAVCR2 in renal clear cell carcinoma." (PMID 36338658, 2022).